IFNG (interferon gamma)
Diseases named in the same sentence as IFNG in open-access papers (continued):
Sharing a sentence is not in itself a finding about the gene and the disease.
tumor (continued). "In tumor tissues, we observed low levels of IFNγ and CD8+ cells, while the tuberculoma showed high levels of CD137+ cells and IFNγ-producing CD8+ T cells." (PMID 38254759, 2024). "Consistently, we found significant associations between lower expression of IFNG, CD40LG, and CXCR5 and larger tumor sizes or adjacent tissue invasion (p = 0.01, p = 0.03 and p = 0.01, respectively)." (PMID 38831317, 2024). "For the tumor surveillance system, T cells which secrete interferon gamma (IFNγ) are of particular importance." (PMID 38731892, 2024). "Mechanistically, dopamine directly binds to D1-like receptors expressed on MDSCs and inhibits IFNγ-mediated iNOS production by both tumour bearing mice and human MDSCs in vitro, leading to enhanced T cell proliferation." (PMID 38464388, 2024). "We found that PD-L2, while similarly inducible by IFNγ as PD-L1, exhibits distinct spatial distribution within the tumor microenvironment, suggesting independent contributions to immune evasion." (PMID 39687608, 2024). "In the degranulation assay, the amount of T cells recognizing tumor cells (CD8+/CD107a+/IFNγ+ cells) was larger in co-cultured compared to unspecifically expanded pTc HROC113 (p = 0.04)." (PMID 39075115, 2024). "We found that TTCS‐conditioned neutrophils exhibited a notable ability to inhibit the proliferation and IFNγ production of tumor‐specific CD8+ T cells, which occurred in a delayed, apoptosis‐dependent manner." (PMID 39447112, 2024). "The role of IFNγ in tumorigenesis is more broad and perhaps more complex; concomitant pro- and anti-tumor functions have been described." (PMID 38962090, 2024). "Recent studies have highlighted the important role of STAT1 in PD-L1-induced tumor immune evasion under IFNγ stimulation." (PMID 38351096, 2024). "The application of IFNγ neutralizing antibodies, knockdown of CXCL9/CXCL10 gene, or CXCR3 blockade of macrophages all cause the attenuation of anti-tumor immune response." (PMID 38787372, 2024). "In parallel, tumor core astrocytes upregulate many anti-inflammatory genes via JAK-STAT and interferon-gamma response, contributing to an immunosuppressive microenvironment that facilitates tumor growth and infiltration." (PMID 38671983, 2024). "To verify these findings, we performed enzyme‐linked immunosorbent assays (ELISA) to evaluate the secretion of IFNγ, one of the most essential effector cytokines released by activated T cells during tumor cell clearance." (PMID 38417121, 2024). "This can be explained by a different activation status of T cells in healthy or tumor samples: Increased expression of granzymes, perforin and IFNγ indicated T cell activation in CD8 T cells from tumor samples versus healthy tissue." (PMID 39516494, 2024). "While STAT3 is known to reduce the anti-tumor activity of NK cells, it is also reported to be essential for IFNγ production and degranulation of NK cells." (PMID 38891037, 2024). "Research has shown that CD8A+ NKT-like cells not only possess cytotoxic granules, indicative of their potential to directly engage and destroy tumor cells, but also secrete high levels of interferon-gamma (IFN-γ) when stimulated by TCR-matched antigens." (PMID 38975339, 2024). "This study reveals that PD-L2, though similarly inducible by IFNγ as PD-L1, displays a distinct spatial distribution within the tumor microenvironment." (PMID 39687608, 2024). "Following tumor inoculation, ASK1 deficiency led to the upregulation of genes related to the immune response, including interferon-gamma (IFN-γ), and revealed the necessity of NK cells for these anti-metastatic effects." (PMID 39090094, 2024). "We detected a stronger pro-inflammatory environment in the lungs than in tumours of IAV-infected tumour-bearing mice, indicated by increased IFNγ, IL-12 and TNFα concentrations." (PMID 38271469, 2024). "NK cell inhibitory ligands can be upregulated on tumor cell surfaces in response to interferon-gamma (IFN-γ), a cytokine which is produced by activated NK cells." (PMID 39205244, 2024).
tumor (continued). "CD8+T cells kill tumor cells by secreting enormous amounts of protease perforin, granzyme B, and interferon-gamma (IFN-γ)." (PMID 38550587, 2024). "To test, in this study, a subcutaneous B16F10 tumor model was established, and IFNγ, the effector cytokine of CD4+ Th1 cells, was in vivo neutralized post cryo-thermal therapy with a monoclonal antibody (mAb)." (PMID 38827732, 2024). "Earlier studies revealed that Interferon gamma (IFNG) plays a critical role in the anti-tumor immune response." (PMID 39080467, 2024). "Classically activated macrophages (e.g., by interferon-γ, IFNγ) can kill tumor cells or elicit destructive tumor responses." (PMID 39402303, 2024). "This can be seen by the increased IFNγ concentration at the edge of the periphery of the tumor (brown) and by zooming in on the interface of T cells and tumor cells at 30.8 h (blue square)." (PMID 38636457, 2024). "Tumor-specific CD8 + T cells exhibited higher expression levels of cytotoxicity-related genes IFNG and GZMK, immune regulators FOS and JUN, and exhaustion markers TIGIT and PDCD1." (PMID 39033098, 2024). "The concentration of IFNγ in the culture supernatant was measured using ELISA, and wells exhibiting IFNγ levels of 100 pg/ml or higher were considered to indicate a tumor-specific immune response." (PMID 38288307, 2024). "AAV-mediated expression of IL-12 led to STAT4 phosphorylation, interferon-γ (IFNγ) production, infiltration of T cells and, ultimately, tumor regression." (PMID 38558809, 2024). "With cancer progression, immune evasion can happen due to IFNγ-triggered genetic instability before tumors become more invasive, suggesting immune cell edit tumor antigenicity." (PMID 38216787, 2024). "As expected, the proliferation rate of CD4+ T cells and CD8+ T cells in the tumor microenvironment from IFNγ+/− cKO mice were considerably rescued by the deletion of IFNγ." (PMID 38167862, 2024). "CD27+ IFNγ-producing γδ T cells utilize glycolytic metabolism for energy, and glucose enhances their anti-tumor activity via mTOR regulation of T-bet, EOMES, and NKG2D expression." (PMID 38816652, 2024). "Overall, our study demonstrates that the perturbation of tumor-infiltrating Tregs through the IFNγ-IFITM3-STAT1 feedback loop is essential for anti-tumor immunity and constitutes a targetable vulnerability of cancer immunotherapy." (PMID 38167862, 2024). "Anti-cancer immunity relies on the effector functions (e.g., IFNγ production) of T cells that reside in a hypoxic tumor microenvironment." (PMID 39477954, 2024). "Taken together, these results suggest that macrophage polarization in the LGG TME can be driven by interferon-gamma activation of the STAT1/IRF1/IRF5 to promote tumor progression in concert with TGFB2 levels." (PMID 38539537, 2024). "T-cell reinvigoration, followed by cytotoxic T-cell infiltration into the tumor nest, release of Interferon gamma (IFNg) and cytolytic proteins (GranzymeB and Perforin) finally leads to tumor cell killing." (PMID 38383563, 2024). "Conversely, CXCL16 exerted pro-tumorigenic effects in BCa by activating the ERK1/ERK2 signaling pathway and promoting tumor proliferation in response to IFNγ." (PMID 39409924, 2024). "Interferon gamma (IFN-γ) is an inflammatory cytokine that plays a key role in tumor immune surveillance." (PMID 38254043, 2024). "Extensive evidence demonstrates that CD8+ CTLs and NK cells can identify and destroy tumor cells through the secretion of perforin, granzymes, and cytokines such as interferon-gamma (IFN-γ) and TNF-α 46, 49-52." (PMID 39664577, 2024). "A similar dual effect on tumor progression has been extensively described for the IFNγ signaling pathway in general." (PMID 38396830, 2024). "APCs and tumor cells differ in the composition of proteasome subunits, with APCs expressing the immunoproteasomes and tumor cells of epithelial origin expressing the immunoproteasomes only under IFNγ stimulation." (PMID 39569190, 2024).
tumor (continued). "In murine systems, the requirement of IFNγ for tumor Nos2 expression has been shown, which was amplified by other cytokines including IL1β and TNFα." (PMID 39356141, 2024). "This differentiation is influenced by the cytokine milieu within the tumor environment; IFNγ and TNFα promote an M1 phenotype, while TGFβ encourages the M2 phenotype." (PMID 38594256, 2024). "Interferon-gamma (IFN-γ)-induced autophagy in tumor cells and CSCs leads to the production of arginine resynthesis precursor asymmetric dimethylarginine (ADMA)." (PMID 39430253, 2024). "Tumor necrosis factor-alpha (TNFα) from T cells and NK cells is also stimulated to reduce IL-4-mediated suppression of IFNγ and upregulate tumor cell MHC I and II expression for enhanced recognition and lysis." (PMID 39697343, 2024). "Effective depletion of CD8 T cells was confirmed by analysis of IFNγ producing T cells within the tumor." (PMID 38267402, 2024). "Several studies have also highlighted that lactate suppressed cytotoxic activity of CD8+ T cells by inhibiting production of IFNγ, which is crucial for facilitating tumor killing by CD8+ T and NK cells." (PMID 38916448, 2024). "We then validated that DRP-104 reduced exhausted T cell populations and improved the functionality of T cells in the tumor microenvironment, as demonstrated by increased IFNγ and TNFα expression." (PMID 38536921, 2024). "Further studies suggested that IFNγ plays a central role not only in direct T cell killing of tumor cells but also in indirect T cell-mediated cytotoxicity via myeloid phagocytosis in the solid tumor microenvironment." (PMID 38893085, 2024). "It has been reported that anti‐PD‐L1 therapy can induce remodeling of the macrophage compartment in responsive tumor models, primarily through increased levels of IFNγ, leading to a more proinflammatory phenotype and enhanced activity of CD8 T cells." (PMID 38434763, 2024). "In vitro studies confirmed the secretion of IFNγ by splenocytes in response to tumor cell challenges, further supporting the anti-tumor efficacy of the vaccines." (PMID 39081320, 2024). "Our results showed that the expression of CXCL9, CXCL10, GZMA, GZMB, PRF1 and IFNG was significantly higher in tumor tissues than in adjacent normal tissues in GC patients." (PMID 39376571, 2024). "It should be emphasized that the immunodynamic or tumor ecodynamic four-factor relationship (IFNγ)(pSTAT1)/(TGFβ)(pSTAT3) or (TGFβ)(pSTAT3)/(IFNγ)(pSTAT1) is a collective linkage behavior, not a single factor action or one-to-one interaction." (PMID 38807760, 2024). "We finally confirmed that Cbx3 KO can increase CRC chemosensitivity under IFNγ stimulation with MC38 syngeneic mouse tumor model." (PMID 38684864, 2024). "We find this increased tumourigenesis is associated with CD3 + T cell infiltration, increased interferon gamma signalling, elevated expression of the IFNγ target IDO1 and increased tryptophan metabolism in Dock2-deficient tumours." (PMID 39242821, 2024). "Prolonged IFNγ exposure induces the overexpression of the inhibitory molecules PD-L1 and PD-L2 and their receptor PD-1 on tumor cells, leading to T-cell exhaustion and attenuation of effector T-cell responses." (PMID 38831317, 2024). "Together, these results indicate that loss of MCJ in IL2-expanded TCR-specific CD8 cells can enhance their antigen-specific anti-tumor-killing activity in vitro by promoting the secretion of IFNγ and their cytotoxic activity." (PMID 38789421, 2024). "Rationale: In adoptive T cell therapy (ACT), the direct cytotoxic effects of CD8 T cells on tumor cells, including the release of interferon-gamma (IFN-γ), are considered the primary mechanism for tumor eradication." (PMID 39629126, 2024). "More importantly, the proportions of tumor‐infiltrating IFNγ+, GZMB+, and TNFα+ CD8+ T cells were significantly elevated after SRC‐1 deletion, indicating more effector CD8+ T cells were activated." (PMID 38953362, 2024).
tumor (continued). "SRC-3 KO in Tregs results in increased infiltration of cytotoxic immune cells into the tumor and elevated levels of IFNγ and CXCL9 in the TME." (PMID 38698860, 2024). "Activation of the interferon gamma (IFN-γ) signaling pathway was observed in MICA+ tumor cells and MMP9+ macrophages." (PMID 38254761, 2024). "Secretion of IFNγ has been shown to be critical for CAR T cell anti-tumour efficacy in the solid tumour setting." (PMID 38600376, 2024). "The APOL3-LDHA axis increases IFNγ levels in colorectal cancer cells, reduces lactate concentration, promotes tumor ferroptosis, and enhances the efficacy of anti-PD-1 immunotherapy." (PMID 39223632, 2024). "Tumor-infiltrating lymphocytes and other immune effectors secrete cytokines such as TNFα and IFNγ, which can activate NFκB and STAT1 signaling in cancer cells." (PMID 39461475, 2024). "Splenocytes from these mice demonstrated higher cell lytic capacity as well as higher IFNγ production, demonstrating an increased anti-tumor activity." (PMID 38803496, 2024). "IFNγ has increased with the number of T cell and tumor cell interactions from a starting concentration of 0 at snapshot 0 h and decreases by the next snapshot (7.7 h) due to some T cells beginning to downregulate TCR and tumor uptake of soluble IFNγ." (PMID 38636457, 2024). "The interaction between TIM3 and galectin 9 (Gal9) in CD8+ T cells leads to the reduction of the production of cytokines (IFNγ, IL-2, and TNFα), the inhibition of T cell proliferation, and the inhibition of anti-tumor immunity." (PMID 39372416, 2024). "Intra-cellular activation of NOD1 in T cells enhances the production of the tumor-suppressing cytokine IFNγ, thereby inhibiting tumorigenesis." (PMID 38523155, 2024). "Functionally, MDSCs hamper anti-tumor immunity by impairing T cell proliferation, IFNγ responses, and NK cell function while facilitating the expansion of regulatory T cells (Tregs), thus contributing to tumor evasion." (PMID 38343540, 2024). "Remarkably, the interaction between attIL12-TILs and autologous tumor cells induced robust levels of IFNγ in vitro and in vivo to suppress TGFβ-induced collagen overexpression and, in turn, to enhance TIL infiltration into tumors." (PMID 39574893, 2024). "STAT1, however, is crucial in NK cell development, IFNγ production, and cytotoxic function, particularly in the tumor microenvironment." (PMID 39349746, 2024). "For example, T cell‐derived interferon γ (IFNγ) can promote tumor FGF2 signal transduction, reduce nicotinamide adenine dinucleotide (NAD+), activate β‐catenin acetylation, and reprogram tumor dormancy." (PMID 38318160, 2024). "In cancer patients and tumor-bearing mice, tumor cells and tumor cell-induced myeloid cells express high levels of PD-L1 in response to IFNγ secreted by tumor-activated T cells." (PMID 38995014, 2024). "Several immune cells express receptors for interferon, and interferon-gamma (IFN-γ) is crucial in promoting a proinflammatory tumor environment and enhancing tumor immunogenicity by inducing M1 macrophages." (PMID 38255296, 2024). "An anti-tumor role for IL-18 (formerly called IFNγ-inducing factor) was also proposed, based on its capacity to stimulate the production of IFN-γ by activated lymphocytes, subsequently enhancing apoptosis of tumor cells." (PMID 38954024, 2024). "IL-17 can also stimulate the production of anti-tumor cytokines, such as interferon-gamma (IFN-γ), which has potent anti-tumor activity." (PMID 38792785, 2024). "IFNγ is species-specific, so that the human IFNγ secreted by the T cells cannot act on mouse tumor stroma cells." (PMID 39776913, 2024). "The next question was how attIL12-TILs induce greater IFNγ production than attIL12-T or control TILs when interacting with tumor cells." (PMID 39574893, 2024). "Concordantly, the CUL5 KO group had a significantly higher number of tumor-infiltrating transferred T cells that were still capable of producing IFNg and/or TNFa upon in vitro re-stimulation than the NC group." (PMID 38242867, 2024).
tumor (continued). "Activated CD8+ T cells migrate to the tumor region to release cytotoxic molecules such as IFNγ, TNFα, perforin, and granzyme B, which activate anti-tumor immune responses and induce apoptosis in tumor cells." (PMID 39776907, 2024). "Interferon gamma (IFN‐γ) is a crucial nexus for controlling PD‐1‐mediated tumor infiltration by T cells, so the increasement of IFN‐γ in Group C and Group E can expand the effect of anti‐PD‐L1 therapy in mice." (PMID 38774946, 2024). "Nevertheless, the opposite is observed in KIRC, where high expression of IFNG, instead of suppressing the tumor, results in lowering the survival rate by almost 1.5 times as compared to its lower expression." (PMID 38638111, 2024). "Within the tumour, tumour-infiltrating lymphocytes are the main source of IFNγ, which have displayed particular importance in tumour immunosurveillance." (PMID 38339377, 2024). "Extensive studies from our group have demonstrated that STAT3, which is persistently activated in multiple types of immune cells in the tumor microenvironment, contributes to the suppression of IFNγ production in the tumor microenvironment." (PMID 39618825, 2024). "Th17 cells express the cytokines IL-17, IL-21, IL-22 and other cytokines such as IFNγ and TNFα in human tumor tissues." (PMID 38833034, 2024). "In some cases, ICB would accelerate tumor progression by promoting IFNγ-induced oncogenic pathways and cancer stemness." (PMID 39256398, 2024). "Research has shown that IFNγ enhances immunosuppressive molecule regulation, tumor MHC expression, and T cell infiltration." (PMID 38928150, 2024). "Critically, CD47 × PD‐L1 BisAb treatment resulted in significantly greater IFNγ‐producing CD8+ T cells in the tumor and spleen than anti‐PD‐L1 alone." (PMID 39584189, 2024). "For instance, acetate produced by Bifidobacterium bifidum and the short-chain fatty acid butyrate were shown to enhance anti-tumor immunity by increasing tumor-infiltrating IFNγ secreting CD8+ T cells." (PMID 38690563, 2024). "In humans, T-bet and Eomes knock-out in NK cells reduce IFNγ, perforin (Prf) and granzyme B (GrzB) production as well as proliferation, thus impairing NK cells anti-tumor function in tumor-bearing NSG mice model." (PMID 39179536, 2024). "Lycopene treatment increases the CD4+/CD8+ ratio in the spleen and promotes IFNγ-expressing CD8+ T cells in tumor tissues." (PMID 38361933, 2024). "Our analysis revealed a notable reduction in CD8+ T cells, NKT cells, and tumor IFNγ levels in EGFRdel/DUSP22 KO tumors." (PMID 38877005, 2024). "Macrophages are usually converted to M1-like TAMs after the action of IFNγ, and TNFα, as well as lipopolysaccharides to exert tumor suppressive effects." (PMID 39776907, 2024). "This indicated that IFNγ is required for the control of tumor growth in the context of ICB, as well as under baseline conditions in the absence of therapy." (PMID 39551601, 2024). "Subsequently, these activated immune cells produced IFNG, a cytokine that is categorized as a tissue modifier and highly correlated with the T cell-inflamed tumor microenvironment." (PMID 39080467, 2024). "Bifidobacterium bifidum can stimulate interleukin-12 (IL-12) production followed by enhanced recruitment of tumor-specific cytotoxic T lymphocytes (CTLs) and concomitant release of interferon-gamma (IFN-γ)." (PMID 38564002, 2024). "DCs, macrophages, and neutrophils exert their tumor cell-killing activity by releasing cytokines such as TNFα, IL-6, and IFNγ." (PMID 39204319, 2024). "T cells secrete interferon gamma (IFNγ) that functions as autocrine/paracrine molecule in response to pembrolizumab in the tumor site." (PMID 38916448, 2024). "Of interest, the majority of patients with higher levels of CD8 T cell infiltration and IFNγ expression in the progressive tumor lesions, did have response to the ICI line given after the biopsy was taken." (PMID 38280045, 2024).